MYC (MYC proto-oncogene, bHLH transcription factor)
Diseases named in the same sentence as MYC in open-access papers (continued):
Sharing a sentence is not in itself a finding about the gene and the disease.
tumor (continued). "In CRC, the JAK/STAT3 pathway can directly regulate tumor immune cells and upregulates the expression of oncogenic proteins, such as c-MYC, Cyclin D1, BCL2 or MCL1 to help drive tumor progression and chemoresistance." (PMID 35501324, 2022). "RNA sequencing revealed a tumor-suppressive role of miR-769-3p by modulating stromal gene expression, such as interferon-gamma-related genes and MYC target gene sets." (PMID 36139534, 2022). "IRF1 has been described as a tumor suppressor in many cancer types and suppresses MYC-driven oncogenesis." (PMID 35453756, 2022). "Critically, the intravenous administration of miR-138 significantly impedes MYC-driven tumor growth in vivo." (PMID 34937878, 2022). "Of note, splenic tumour burden, as assessed by flow cytometry, was correlated with spleen length and serum paraprotein levels, suggesting splenic tumour growth is a major contributor of whole-body tumour burden in the Vk*MYC model." (PMID 35908046, 2022). "Tumor cells (CD45−, EPCAM+) in the MYC-OFF state displayed significantly more surface MHC-I protein than MYC-ON tumor cells." (PMID 35760778, 2022). "Together, these studies place PP2A as a critical mediator of both epigenetic and post-translational regulation of MYC during tumor progression." (PMID 35118387, 2022). "This switch would operate not only in breast cancer tumors or in other human tumor types but also in other species for which the lysosomal program is controlled through a competition between MYC and other bHLH-zip factors." (PMID 35351824, 2022). "In tumor cells c-MYC expression is often deregulated and the resulting unscheduled DNA replication causes DNA damage and genomic instability." (PMID 35624466, 2022). "Myeloid cell-specific ablation of FBXW7 enhances tumor proliferation by decreasing its ubiquitination on c-MYC, which promotes TAM polarization." (PMID 35515121, 2022). "For example, trametinib inhibition of the MEK-ERK pathway in many tumor cells leads to a rapid degradation of c-MYC and transcriptional reprogramming that in some tumor cells can be 15–20% of the transcriptome, effectively changing the tumor cell phenotype." (PMID 34958800, 2022). "We found that Hgma1 is upregulated in Myc-R26Met compared with Alb-R26Met tumours, consistent with its involvement in MYC regulation as recently reported." (PMID 36433941, 2022). "While WB1P and WB1P-Myc tumors both resemble TNBCs, the latency from tumor induction to outgrowth is greatly reduced upon MYC overexpression." (PMID 36323660, 2022). "Further studies are mandatory to better understand the role of circPVT1 in oncogenesis as well as its functional contribution to circPVT1/lncPVT1 and c-MYC axis in tumor progression." (PMID 35090471, 2022). "We also observed increased tumor infiltration of CD8+ T cells in the MYC-OFF state, while the infiltration by other immune subtypes was not significantly altered." (PMID 35760778, 2022).
tumor (continued). "Even though both ATRT-SHH and MYC tumors arise from Smarcb1-negative Sox2-positive precursor cells, Sox2 expression levels in the tumor itself vary between the tumor subgroups of both murine and human samples." (PMID 35318328, 2022). "In contrast, MYC overexpression suppresses the migration of CD8+ T cells in a tumor cell-intrinsic manner." (PMID 36323660, 2022). "This is perhaps expected given the enrichment of pro-proliferative programs found in MYC-enriched tumor areas." (PMID 35013227, 2022). "In some tumors like PCa, upregulation and the interplay between MYC, AR, and the mTOR mutations cause Gln addiction when Gln becomes a conditional EAA for tumor growth and survival." (PMID 33401748, 2021). "Similar findings have been observed in multiple myeloma, where the combination of Decitabine and HDACi Quisinostat reduced MDSC and induced temporal changes in memory T cells in the bone marrow while reducing MYC expression in tumor cells." (PMID 33859645, 2021). "In this study, we report that MYC stimulates cholesterol production and promotes tumor cell proliferation via transcriptionally upregulating SQLE." (PMID 33791309, 2021). "Recent studies indicate that MGA function is consistent with it acting as a MYC antagonist and tumor suppressor." (PMID 34236315, 2021). "To tease these changes apart from those more closely connected to the MYC–HCF-1 interaction, we overlaid tumor RNA-Seq with that generated for the 4A MYC mutant in vitro." (PMID 33416496, 2021). "Another lncRNA affecting MYC expression in various tumor types is NEAT1, which forms specific nuclear structures called paraspeckles." (PMID 34440124, 2021). "By eliciting immunoresponse and blocking angiogenesis, MYC inhibition can also modify the tumor microenvironment." (PMID 33801599, 2021). "They reported that DDEF1 gene, located at chromosome 8q24, was increased in 8q amplified tumor whereas MYC expression remained unchanged." (PMID 34830903, 2021). "The classic role of MGA was a TSG that suppressed the progress of tumors by binding to MAX and inhibiting MYC-dependent tumor development." (PMID 34733843, 2021). "The results showed that the FRlncRNAs signature mainly involved DNA repair, glycolysis, MYC targets, and tumor-related signaling pathways." (PMID 34178478, 2021). "This review describes both the pivotal role of MYC in physiology and tumor development, and MYC-targeted anticancer therapies." (PMID 33801599, 2021). "For instance, cells following transformation induced by MYC activated autophagy due to mitochondrial stress, inhibiting tumour growth in vitro and in vivo." (PMID 34445233, 2021). "This is due to their ability to carry cargos like MYC between tumor cells, inducing leukemic progression." (PMID 34372899, 2021). "In these cancers, miR-145 inhibits tumor proliferation by inhibiting the MYC and Friend leukemia virus integration 1 (FLI-1) genes." (PMID 34830370, 2021). "Most attention has been paid to selective targeting of critical oncogenic drivers such as MYC in multiple tumour types by BETi." (PMID 34681760, 2021). "The uniqueness of MB2 will likely result in very specific therapeutic compounds with minimal off-target effects, and its essentiality assures that tumor cells cannot escape a treatment strategy that targets MYC’s MB2 in cancer." (PMID 34676047, 2021). "In tumor cells overexpressing MYC, increased MYC levels lead to saturation of the same promoters but also to enhancers of active genes (a phenomenon known as “invasion”), as reported by other previous studies." (PMID 33801599, 2021). "We conclude that the interaction of MYC with HCF-1 is essential for tumor maintenance in this context." (PMID 33416496, 2021).
tumor (continued). "A greater insight into key functions mediated by MYC in tumor environment is crucial for the development of more effective therapeutic approaches." (PMID 33801599, 2021). "SIX1 activates the transcription of potent oncogenes and stem cell regulators, such as c-MYC and ezrin, that have a vital role in tumor invasion and signal transduction in many cancers." (PMID 34771571, 2021). "In this review, we summarize current data on the regulation of MYC by various non-coding RNAs that can potentially be targeted in specific tumor types." (PMID 34440124, 2021). "Although there are currently no ‘direct’ MYC inhibitors used in clinical practice, multiple approaches have been reported that can successfully modulate MYC activity in tumour cells, belying the undruggable label." (PMID 33799592, 2021). "Differential expression analysis revealed lower expression of genes in metabolic pathways, mTOR, MYC, and AR pathways in the Castrated group compared to the Intact tumor groups." (PMID 33602919, 2021). "Reexpression of stemness marker genes, such as c-MYC, which is a WNT target, in the murine intestine caused tumor initiation together with dedifferentiation and triggered stem cell-like properties in gastric cells." (PMID 34488885, 2021). "Perhaps the most convincing evidence supporting a role for BIM induction in mediating the tumour suppressive function of MYC was provided in experiments using MYC mutants incapable of inducing the expression of this pro-apoptotic protein." (PMID 33799592, 2021). "In the previous section, we mentioned the importance of MYC from both tumor-extrinsic and -intrinsic sides." (PMID 34122516, 2021). "Expression levels of the GLS1 and MYC gene in tumor tissues and amino acid concentrations in blood plasma were correlated to a progression-free survival in PCa patients." (PMID 34335968, 2021). "The discovery of new components affecting the N-Myc protein stability aroused great interest concerning the possibility of developing novel treatments against many MYC-driven tumours." (PMID 34884690, 2021). "Currently, the main highlighted and reoccurring regulatory interactions with tumor-promoting signaling pathways are Wnt/β-catenin and MYC." (PMID 34830370, 2021). "Induction of p27 by miR-124 decreases phosphorylated Rb and c-MYC protein levels leading to cell cycle arrest in vitro and reduced tumor growth in vivo." (PMID 33718147, 2021). "While in normal cells the levels of MYC RNA and protein are tightly regulated, in tumor cells they are aberrantly expressed." (PMID 34359754, 2021). "When large tumors were treated with doxycycline to inactivate MYC, RLuc measurements showed that tumor initially regressed but ultimately recurred." (PMID 33446671, 2021). "In mice models, inhibition of HMG-CoA reductase by statin inhibits tumor initiation and growth by blocking MYC phosphorylation and activation." (PMID 33804425, 2021). "Deregulated and enhanced expression of MYC is a driver of colorectal tumorigenesis, necessitating strategies to inhibit MYC function or expression for tumor therapy." (PMID 33078202, 2021). "For instance, curcumin induces transcriptional activation of the tumor-suppressive micro RNA miR-34a, which is paralleled by downregulation of MYC, β-catenin, insulin, and IGFR mRNAs." (PMID 33937075, 2021). "Targeted next generation sequencing revealed MYC amplification in the EBV-positive component of the tumor and HER2 amplification in the EBV-negative part." (PMID 33653296, 2021). "CUDC-907 is a dual PI3K and HDAC inhibitor, and previous studies have demonstrated that HDAC inhibitors act synergistically with PI3K inhibitors to inhibit tumor growth in an MYC-dependent manner in different types of cancer." (PMID 34776939, 2021).
tumor (continued). "(A–C) Box plots of MYC (A), NFKB1 (B), and STAT3 (C) expression in tumor-associated stroma from the GSE14548 dataset by disease grade (grade 1: G1; grade 2: G2; grade 3: G3)." (PMID 34169837, 2021). "Using cutoff values of 40%, 50%, and 50% positive tumor cells for MYC, BCL-2, and BCL-6, respectively, 108 (55.4%) were positive for MYC, 129 (66.2%) cases were positive for BCL-2, and 115 (58.9%) cases were positive for BCL-6." (PMID 34804942, 2021). "Although it is known that c-MYC is a crucial downstream effector of oncogenic KRAS in other tumor types, the biological importance of this transcription factor in PDAC had not been acknowledged until recently." (PMID 34491463, 2021). "MYC facilitates tumor progression by modulating the expression of genes that are involved in the cellular metabolism of tumor cells." (PMID 33889549, 2021). "Approaches that result in decreased MYC expression have been shown to significantly impact tumor viability while offering a notable therapeutic window and overall safe profile." (PMID 34577013, 2021). "JQ1, a small molecule inhibitor that blocks BRD4 and c-MYC expression and promotes apoptosis, was recently reported to suppress cancer cell invasion and migration as well as tumor metastasis 13,14." (PMID 34803511, 2021). "The response of FaDu tumor cells to combined treatment with CisPt + RSV led to the significant amplification of c-MYC gene expression, an antagonist effect to the one induced by CisPt (p < 0.009, **) or RSV (p < 0.007, **) used separately." (PMID 34204834, 2021). "Our research found that HOXB5 inhibited the key genes CCND1 and MYC in the Wnt/β-Catenin signaling pathway, inhibited the tumor's occurrence, and inhibited the classical cancer pathway RTK pathway to inhibit cancer and improve OS." (PMID 34306077, 2021). "The pro-apoptotic tumor suppressor BIN1 inhibits the activities of the neoplastic transcription factor MYC, poly (ADP-ribose) polymerase-1 (PARP1), and ATM Ser/Thr kinase (ATM) by separate mechanisms." (PMID 34948122, 2021). "SIRT2 is also considered a BC tumor suppressor, and can participate in metabolic dysregulation indirectly by stabilizing MYC via deacetylation of a repressor, which functions as a positive feedback loop." (PMID 34072826, 2021). "Following intraperitoneal administration of doxycycline, we measured the MYC inactivation rate in vivo by acquiring a tissue biopsy of the same tumor at various times and measuring the amount of MYC mRNA via qPCR." (PMID 33446671, 2021). "Molecular subtyping based on transcriptomics was able to group NKTCLs into three subtypes with association to survival: Tumor-suppressor/immune-modulator (TSIM), MYC-related (MB), and Histone epigenetic altered (HEA) groups." (PMID 34440582, 2021). "Such evidence underscores plasticity between an MYC-driven proliferative, yet non-invasive, tumor core versus a less proliferative but invasive, NFkB-driven tumor rim." (PMID 33805316, 2021). "TERT and MYC mRNA abundance was positively correlated (ρ = 0.27; P = 1.46 × 10−3) but MYC abundance was unrelated to tumour TL." (PMID 34824250, 2021). "High levels of MYC induce proliferation of tumor cells and stimulate the transcription of genes involved in mitochondria biogenesis and glycolysis, thus promoting metabolic reprograming of cancer cells." (PMID 34944772, 2021). "The proto-oncogene MYC was also detectable on protein level independent to the parental tumor tissue, particularly with a nuclear localization." (PMID 33800955, 2021).
tumor (continued). "Although MYC promotes rapid cellular growth leading to tumor metastasis, the interaction between the tumor and its microenvironment often contributes to drug resistance and subsequent relapse." (PMID 34556188, 2021). "Nevertheless, TNKSi predominantly leads to cell type-dependent and primary inhibition of the WNT/β-catenin, YAP, and PI3K/AKT signaling pathways and, subsequently, counteraction of MYC-driven cell cycle progression and tumor cell growth." (PMID 34337362, 2021). "For this reason, we analyzed how treatment with RSV and/or CisPt affected c-MYC expression in tumor cells as compared to normal cells." (PMID 34204834, 2021). "This review describes different types of RNA that control MYC gene expression in different tissues and tumor types." (PMID 34440124, 2021). "This miRNA belongs to the miR-17~92 cluster, whose expression is controlled by the MYC transcription factor and triggers the proliferation of tumor cells." (PMID 33429910, 2021). "According to The Cancer Genome Atlas (TCGA), MYC amplification occurs in 21% of all tumor samples, whereas that of the MYCN and MYCL paralogs are much less frequent." (PMID 34503295, 2021). "Recently, it was shown that ssDNA is also carried by microvesicles to recapitulate genomic aberrations; for example, microvesicle-trafficked ssDNA can amplify the oncogenes (i.e., MYC) of the primary tumor." (PMID 34599143, 2021). "Quantitative polymerase chain reaction (qPCR) analysis on an independent set of primary human lung biopsy samples confirmed that MYC is highly expressed in LSCC tumours compared with normal lung tissue." (PMID 34636321, 2021). "The reactivation of MYC in mammary epithelial cells is able to downregulate lineage specific TFs to reprogram the cell to a stem cell-like state favoring tumor initiation and progression." (PMID 34249759, 2021). "MYC-driven functions in tumor initiation and progression also depend on transcriptional repression of target genes and recruitment of chromatin modifying factors." (PMID 33801599, 2021). "Suppression of MYU RNA expression resulted in decreased levels of MYC expression and suppression of tumor cell proliferation." (PMID 34440124, 2021). "The simplified 3-compartment model is the minimal model to account for tumor growth, regression, relapse, as well as the kinetics of MYC inactivation and escape, during the time course of doxycycline treatment." (PMID 33446671, 2021). "MYC was transcriptionally upregulated in human LSCC compared to healthy lung tissue or LADC tumours." (PMID 34636321, 2021). "Experiments using MyC-CaP tumours in FVB mice as a second tumour model demonstrated a similar trend towards enhanced tumour perfusion at 7 days post-FRT." (PMID 34155340, 2021). "The combined inhibition of epi-factors, e.g., P300/CBP (by GNE-781) and BRD4 (by OTX015), have been also applied for decommissioning oncogenic enhancers (e.g., MYC enhancers), and can increase the anti-tumour efficacy." (PMID 34298745, 2021). "As we and other groups have shown, stabilization of the higher-order genomic structure—the G-quadruplex (G4)—in the G/C-rich proximal region of the MYC promoter is an established approach to decreasing transcription and facilitating tumor lysis." (PMID 34577013, 2021). "Cluster 1 and Cluster 3 was significantly enriched in carcinogenic activation and tumor proliferation related pathways, including E2F_target, G2M_checkpoint and MYC_target." (PMID 34872577, 2021).